VNN1 (vanin 1)
Diseases named in the same sentence as VNN1 in open-access papers (continued):
Sharing a sentence is not in itself a finding about the gene and the disease.
renal fibrosis (2 papers, 2018 to 2022). A final common manifestation of a wide variety of chronic kidney diseases characterized by glomerulosclerosis and tubulointerstitial fibrosis. "This study aimed to evaluate the usefulness of vanin-1 and periostin in urine as markers of the autoimmune process in kidneys and renal fibrosis in IgA nephropathy (IgAN) and IgA vasculitis with nephritis (IgAVN)." (PMID 35268356, 2022). "This study aimed to evaluate the significance of vanin-1 and periostin in urine for the autoimmune inflammatory process in kidneys and renal fibrosis in IgAN and IgAVN." (PMID 35268356, 2022). "In this study, we showed the role of vanin-1 in the induction of tubular damage and subsequent renal fibrosis using rats with UUO." (PMID 30332759, 2018). "In the kidney tissue, the mRNA and protein expressions of vanin-1 significantly decreased, whereas there was increased expression of transforming growth factor (TGF)-β1 and Snail-1, which plays a pivotal role in the pathogenesis of renal fibrosis via epithelial-to-mesenchymal transition (EMT)." (PMID 30332759, 2018).
soft tissue sarcoma (2 papers, 2018 to 2025). A malignant neoplasm arising from muscle tissue, adipose tissue, blood vessels, fibrous tissue, or other supportive tissues excluding the bones. "Giessner and co-workers identified Vnn1, a pantetheinase, as a tumor suppressor for the development of aggressive forms of soft tissue sarcomas." (PMID 40943172, 2025). "By combining new genetic models with transcriptomic, metabolomic, and electron microscopy approaches, we identified the Vnn1 pantetheinase as a tumor suppressor for the development of aggressive soft tissue sarcomas (STS)." (PMID 30456364, 2018).
type 1 diabetes (2 papers, 2023 to 2024). "On the genes in low expression group of VNN1 were mainly enriched in ribosome, graft-versus-host disease, type I diabetes mellitus, autoimmune thyroid disease, and allograft rejection." (PMID 37608823, 2023).
adenoma (1 paper, 2025). A neoplasm arising from the epithelium. "The expression of Vnn1 and Crtac1 was further enhanced by neonatal irradiation, which may have contributed to the transition from hyperplasia to adenoma observed in the 1w12Gy group." (PMID 40076501, 2025).
bone sarcoma (1 paper, 2023). A sarcoma that arises from the bone. "Conversely, in human bone sarcomas, VNN1 expression does not correlate with prognosis, and Pant does not control tumor growth in mice." (PMID 37833072, 2023).
breast tumor (1 paper, 2024). "However, CYR61, FLRT2, SLIT2, VNN1, MAP1B, MYLK, and TUBA1A gene expressions were high in normal adjacent tissue in comparison with those in breast tumor tissue." (PMID 39596804, 2024).
coccidiosis (1 paper, 2011). A parasitic infection caused by Coccidia. "Vanin 1 is of interest for further studies aimed at characterizing the host response to coccidiosis since we observed at least a 2-fold reduction in serum concentrations of this protein in response to infection with all 3 species of Eimeria, with the biggest drop in response to E. tenella infection." (PMID 21297942, 2011).
coronary artery disease (1 paper, 2025). "A recent study reported that patients with coronary artery disease had elevated plasma vanin-1 concentrations, which were linked to both the presence and severity of coronary artery disease." (PMID 40954177, 2025).
COVID-19 (1 paper, 2024). A disease caused by infection with severe acute respiratory syndrome coronavirus 2. "Importantly, VNN1 was associated with the progression of severe COVID-19, showing a strong correlation with clinical indicators and immune cell infiltration." (PMID 39639868, 2024). "Our findings highlight VNN1’s association with key clinical markers and its correlation with increased neutrophils and decreased lymphocytes, indicating its critical role in exacerbating COVID-19." (PMID 39639868, 2024). "Our analysis revealed a significant increase in VNN1 transcription levels in COVID-19 patients compared to the control group." (PMID 39639868, 2024). "Single-cell sequencing showed VNN1 predominantly expressed in neutrophils, potentially influencing other immune cells and affecting COVID-19 prognosis." (PMID 39639868, 2024). "In conclusion, our research elucidates the complex interplay between TB and COVID-19, highlighting shared mechanisms and identifying VNN1 as a key factor in disease progression." (PMID 39639868, 2024). "This suggests that VNN1 plays a crucial role in the progression of COVID-19 patients to a critical condition, indicating its potential as a biological marker for disease detection and as an important therapeutic target." (PMID 39639868, 2024). "The identification of potential drugs targeting VNN1 sets the stage for future therapeutic interventions aimed at mitigating the severity of COVID-19." (PMID 39639868, 2024). "Future studies involving in vitro and in vivo experiments would be valuable to validate our findings and explore the mechanistic details of VNN1’s role in COVID-19 progression." (PMID 39639868, 2024). "The GSE217948 dataset also demonstrated a significant upregulation of VNN1 in COVID-19 patients (p < 0.001), while the GSE152418 dataset showed a modest increase (p = 0.041)." (PMID 39639868, 2024). "Prospective clinical studies would be necessary to fully establish the clinical utility of VNN1 as a biomarker or therapeutic target in COVID-19." (PMID 39639868, 2024). "Notably, VNN1 showed predominant expression in neutrophils, significantly upregulated in severe COVID-19 cases compared to controls." (PMID 39639868, 2024). "Finally, in the GSE171110 dataset, VNN1 transcript levels was significantly higher in COVID-19 patients (p < 0.001), reinforcing our findings across multiple datasets." (PMID 39639868, 2024). "Compounds such as clofop, fluticasone, etynodiol, phenol, cefoxitin, (-)-isoprenaline, ciglitazone, and clidinium bromide emerged as promising candidates that may influence VNN1 activity, opening avenues for novel therapeutic strategies against COVID-19." (PMID 39639868, 2024). "In the qRT-PCR analysis, the relative transcription levels of VNN1 were significantly higher in the severe COVID-19 group (p < 0.001) compared to both the control and mild COVID-19 groups, indicating a potential correlation between VNN1 expression and disease severity." (PMID 39639868, 2024). "A negative correlation was observed between high VNN1 transcript levels and both H45 and DOMV, suggesting its significance in predicting poorer outcomes in severe COVID-19 cases." (PMID 39639868, 2024).
depression (1 paper, 2022). "Particularly relevant, given the important role of B2RAN2 (highly similar to vanin-1) and endoglin in oxidative stress and the immune system, they may play roles in depression, being suggested as potential candidate biomarkers to distinguish between MDD and BP." (PMID 35628270, 2022).
endometritis (1 paper, 2016). An acute or chronic, usually bacterial infectious process affecting the endometrium. "It is proposed that VNN1 have innate immune functions and might contribute to tissue injury in endometritis." (PMID 27829441, 2016).
fibrosarcoma (1 paper, 2018). A malignant mesenchymal fibroblastic neoplasm affecting the soft tissue and bone. "Whereas p16p19−/− mice developed various tumor types with a majority of lymphomas, p16/p19/Vnn1−/− mice predominantly developed skin STS typed as fibrosarcomas." (PMID 30456364, 2018).
Hepatoma (1 paper, 2024). "Detected the lipid deposition via oil red staining and analysis the content of triglycerides (TG), low-density lipoprotein-C (LDL-C), and high-density lipoprotein-C (HDL-C) after VNN1 knockout in Leghorn Male Hepatoma cell line." (PMID 37946431, 2024). "Next, knocked out VNN1 via CRISPR/Cas9 system in the chicken Leghorn Male Hepatoma cell line." (PMID 37946431, 2024).
Impaired glucose tolerance (1 paper, 2025). An abnormal resistance to glucose, i.e., a reduction in the ability to maintain glucose levels in the blood stream within normal limits following oral or intravenous administration of glucose. "Notably, vanin-1 levels demonstrated a stronger positive correlation with HbA1c in the highest tertile compared to the correlation in the whole dataset, as indicated by a higher correlation coefficient, suggesting a potential link between elevated vanin-1 and impaired glucose tolerance." (PMID 40954177, 2025).
injury (1 paper, 2019). Damage inflicted on the body as the direct or indirect result of an external force, with or without disruption of structural continuity. "However, even with such mild kidney injury, RP vanin-1 levels, but no other AKI biomarkers, detected the presence of kidney injury." (PMID 30791405, 2019).
ischemia reperfusion injury (1 paper, 2021). Adverse functional, metabolic, or structural changes in ischemic tissues resulting from the restoration of blood flow to the tissue (reperfusion), including swelling; hemorrhage; necrosis; and damage from free radicals. "Indeed, a recent study showed that pharmacological inhibition of vanin-1 is not protective in models of acute and chronic kidney injury using ischemia-reperfusion injury mice." (PMID 34768879, 2021).
joint diseases (1 paper, 2020). "VNN1 has been studied in many different inflammatory diseases showing that it has either a protective or a sensitizing role, but the role in joint diseases has not been studied." (PMID 32434555, 2020).
leukemia (1 paper, 2025). A malignant (clonal) hematologic disorder, involving hematopoietic stem cells and characterized by the presence of primitive or atypical myeloid or lymphoid cells in the bone marrow and the blood. "VNN1 (cg01052291), although not directly linked to AML previously, is implicated in oxidative stress and immune regulation in chronic ITP, suggesting a potential role in leukemia-related inflammation or oxidative stress mechanisms." (PMID 40730747, 2025).
liver cancer (1 paper, 2024). An epithelial or non-epithelial malignant neoplasm that arises from the liver. "This situation exists in a wide range; for example, after knocking down the gene in hepatitis B virus S gene, chicken liver cancer cell lines LMH VNN1 gene, and early rat embryos ISCA1 gene, the expression of knockdown proteins can still be detected by Western blot." (PMID 38203840, 2024).
lung carcinoma (1 paper, 2022).
osteoporosis (1 paper, 2024). A condition of reduced bone mass, with decreased cortical thickness and a decrease in the number and size of the trabeculae of cancellous bone (but normal chemical composition), resulting in increased fracture incidence. "However, VNN1 has been less studied in osteoporosis, and our study examined VNN1 levels in patients and mice with osteoporosis." (PMID 38966541, 2024). "Immunofluorescence and Western blot show that VNN1 is upregulated in the pancreas and bones of T2DM model mice and osteoporosis model mice." (PMID 38966541, 2024). "VNN1 is an emerging biomarker that has not yet been detected in diabetic osteoporosis patients, so we chose VNN1 for further study." (PMID 38966541, 2024).
osteosarcoma (1 paper, 2023). A usually aggressive malignant bone-forming mesenchymal neoplasm, predominantly affecting adolescents and young adults. "In humans, VNN1 expression correlates with improved survival and immune cell infiltration in soft-tissue sarcomas, but not in osteosarcomas." (PMID 37833072, 2023).
rectal cancer (1 paper, 2021). A primary or metastatic malignant neoplasm that affects the rectum. "Many studies have focused on identifying genes as biomarkers associated with tumor response and survival prognosis of rectal cancer patients with pCRT, such as SERPINB5, CHD4, TCN1, VNN1, EPHA4, PCSK1, and DUOX2 genes." (PMID 33506057, 2021). "Currently, a lot of previous studies have reported that genes SERPINB5, CHD4, TCN1, VNN1, EPHA4, PCSK1, and DUOX2 as prognostic biomarkers were proven to correlate with poor tumor response and survival prognosis in patients with rectal cancer receiving pCRT." (PMID 33506057, 2021).
spondyloarthropathy (1 paper, 2024). A group of inflammatory rheumatic diseases associated with arthritis and enthesitis, and often involving the axial skeleton. "In addition, Vanin-1 knockout corrected the increase in chondrogenesis in ank/ank (an animal model of spondyloarthropathy) bone marrow mesenchymal stromal cells (BMSCs) as well as the increase in chondrogenic transdifferentiation and calcification in ank/ank aortic smooth muscle cell explants." (PMID 38966541, 2024).
tumor (18 papers, 2009 to 2025). "In the meantime, some previous studies have reported that the VNN1 gene is associated with the prognosis of certain tumors and tumor-related complications." (PMID 37608823, 2023). "To investigate the mechanisms underlying the tumor suppressive effect of Vnn1 on STS, we performed unbiased metabolomics and transcriptomic analyses of tumors." (PMID 30456364, 2018). "Their group later investigated the functional mechanisms of VNN1 in the pathogenesis of PCa-associated DM, and disclosed that overexpression of VNN1 in the tumor tissues decreased glutathione concentration, increased reactive oxygen species (ROS), then aggravated paraneoplastic islet dysfunction." (PMID 32784500, 2020). "The cysteamine released by Vnn1 pantetheinase limits glycolysis and lactate formation, antagonizing the Warburg effect and thereby limiting cell growth while enhancing tumor cell differentiation and innate immune cell activation." (PMID 30456364, 2018). "Expression of the Vnn1 pantetheinase by sarcomas is tumor suppressive by limiting the use of aerobic glycolysis for growth and rescuing mitochondrial activity through CoA regeneration." (PMID 30456364, 2018). "Our results provide the first experimental evidence that the two products of pantetheinase activity exert complementary effects on the tumor, explaining the basis for Vnn1's suppression on tumor growth." (PMID 30456364, 2018). "Although studies have suggested that the expression of Vnn1 serves as a biomarker for tumor prognosis, the roles of VNN1 in carcinogenesis, if any, are unknown." (PMID 40076501, 2025). "Furthermore, in mouse models, Vnn1-expressing tumor lines are less aggressive, show improved mitochondrial activity, and are enriched in immune transcriptional signatures." (PMID 37833072, 2023). "VNN1 expression was heterogeneous across the cohort, with a range of intensities over 20 units on the log2 scale, allowing the search for correlations with tumor variables." (PMID 37833072, 2023). "However, the value of VNN1 in the diagnosis of tumors and the evaluation of the prognosis of tumor patients’ needs further clinical verification research." (PMID 37608823, 2023). "Likewise, among overrepresented proteins identified in TEX, pantetheinase, encoded by the vanin-1 gene, can serve as a possible serum biomarker for MDV tumor development." (PMID 30764491, 2019). "Altogether, these results show that R and VR tumors do not show the same adaptation potential and that expression of Vnn1 presets cells in a metabolic state that allows them to maintain mitochondrial organization/activity in a tumor and likely stressed environment." (PMID 30456364, 2018). "These genes are involved in the regulation of immune/inflammatory response (Lgals1, Ptgds, Tff2, Ubd), tumor angiogenesis (Lgals1, Esm1, Ndrg1), epidermal growth factor signaling (Erbb4, Nrg1), response to tissue injury (Tff2, Vnn1), and gene transcription (Id3, Ifrd1)." (PMID 19340302, 2009). "To test the contribution of Vnn1 to spontaneous tumor development, we compared mouse survival and tumor incidence in three independent cohorts of p16/p19/Vnn1−/− versus p16/p19−/− mice, derived from two independently derived crosses between p16/p19−/− and Vnn1−/− mice." (PMID 30456364, 2018). "Both ACHE and VNN1 were found to be significantly upregulated in AEG tumor tissues compared with NAT, and ACHE expression was correlated with the grade of tumor differentiation." (PMID 40963562, 2025). "Taken together, these results point to Vnn1 as a novel biomarker for STS prognosis, and it suggests a new route to regulate tumor growth rates through the modulation of CoA and cysteamine levels." (PMID 30456364, 2018). "VNN1 gene expression was higher in the A3 and A5 cell lines than in the T2 cell line, corroborating the response to radiation before and during tumor formation but not in the malignant stage of the model." (PMID 39596804, 2024).
tumor (continued). "In the only case of skin STS (grade III) observed in Vnn1+/+ mice, a low level of Vnn1 transcript was detected by qRT–PCR (not shown), indicating that few cells express Vnn1 in the tumor mass." (PMID 30456364, 2018). "Given the slow rate of tumor development and the rare emergence of STS in Vnn1+/+ mice, we developed new transplantable STS models derived from primary myofibroblasts, previously shown to express Vnn1 in the context of an ischemic stress." (PMID 30456364, 2018). "Three independent myofibroblast tumor lines (J2A, H1, or I1) were obtained which express comparable levels of RasV12-GFP chimeric protein (R) coupled or not to wild-type (VR) or catalytically deficient (VdR) Vnn1 protein at the cell membrane." (PMID 30456364, 2018).
cancer (12 papers, 2014 to 2025). A tumor composed of atypical neoplastic, often pleomorphic cells that invade other tissues. "VNN1 expression showed correlations with stromal scores, immune scores, and cancer purity in different types of tumors." (PMID 37608823, 2023). "There was a decrease in expression of a number of anti-cancer genes (e.g., Casp3, Mgmt, Parp1, Ptpn11) as well as an increase in several cancer-promoting genes (e.g., Ly6a, Lgr5, Vnn1)." (PMID 38151490, 2023). "Several cancer-promoting genes were uperegulated (Ctgf, H19, Mmp12, Mybl1, Vnn1) while cancer inhibiting genes (Cish, Dkk4, Onecut1, Scara5, Socs3, Wif1) were suppressed." (PMID 26200659, 2015). "The HFDs also affected the expression of cancer-related genes in the proximal colon (and other parts of the intestines) including Vnn1 (vanin 1), a pantetheinase with roles in oxidative stress and inflammation 35, and Tnfsf10 (tumor necrosis factor ligand superfamily, member 10)." (PMID 37886485, 2023). "For instance, the pattern of PRSS3 downregulation associated with the clinical relevance of HCC patients was similar to that of TMEM45A and VNN1, which are positively co-expressed genes of PRSS3 in HCC patients showing oncogenic effects on cancer-associated events." (PMID 35480112, 2022). "In terms of cancer-driven mutations, the HRSI group has two significant mutations, including HRAS and KLF5, while the LRSI group has three significant mutations, including ATP6V0A2, BSX, and VNN1." (PMID 34504628, 2021). "Cell-surface proteases, such as ADAM12, VNN1, and FLRT2, would cleave ECM components with the aid of SLIT2, CYR61, and ADAM12 in response to mechanical stimuli, allowing for cancer cells to migrate more easily." (PMID 39596804, 2024). "Cancers are often viewed as never-healing wounds and we anticipated that Vnn1 expression might be induced in some tumors and impact their progression through metabolic rewiring." (PMID 30456364, 2018).